RNU6-1064P (RNA, U6 small nuclear 1064, pseudogene)
Gene: Small nuclear RNA gene on chromosome 9 (107,797,744 to 107,797,847, reverse strand). Ensembl gene ENSG00000222558.
Homologues: Orthologues: chimpanzee U6 (100% identical), macaque U6 (96% identical), mouse Gm23975 (83% identical), guinea pig U6 (77% identical). Paralogues in human: RNU6-698P (88% identical), RNU6-1060P (87% identical), RNU6-116P (87% identical), RNU6-15P (87% identical), RNU6-266P (87% identical), RNU6-345P (87% identical), RNU6-142P (86% identical), RNU6-166P (86% identical), RNU6-188P (86% identical), RNU6-199P (86% identical), RNU6-25P (86% identical), RNU6-29P (86% identical), and 1287 more.